SP2 (Sp2 transcription factor)
Diseases named in the same sentence as SP2 in open-access papers (continued):
Sharing a sentence is not in itself a finding about the gene and the disease.
triple-negative breast carcinoma (1 paper, 2023). An invasive breast carcinoma which is negative for expression of estrogen receptor (ER), progesterone receptor (PR), and human epidermal growth factor receptor 2 (HER2). "The complete loss of both ER and PR led to the generation of a triple-negative breast cancer (TNBC) phenotype in fractions originating from SP1, SP2, and MP2." (PMID 36834918, 2023).
cancer (17 papers, 2017 to 2025). A tumor composed of atypical neoplastic, often pleomorphic cells that invade other tissues. "SP2 is a renowned transcription factor, over-expressed in several human cancers, and implicated in an ample variety of essentially biological processes including cell growth, differentiation, apoptosis and carcinogenesis." (PMID 37056929, 2023). "Therefore, PBMC genetically engineered to express sp1- and sp2-specific TCRs were co-cultured with a series of cancer cell lines that harbored the G12V mutation within the KRAS gene." (PMID 33875134, 2021). "Additional cancer-relevant transcriptional regulators higher in responders before vaccination include SP2, NFYC, AKNA, MYPOP, and ZNF652." (PMID 39450169, 2024). "The specificity protein (Sp) transcription factors (TFs) Sp1, Sp2, Sp3 and Sp4 exhibit structural and functional similarities in cancer cells and extensive studies of Sp1 show that it is a negative prognostic factor for patients with multiple tumor types." (PMID 36982239, 2023). "In total, six of the seven co-regulated genes and Sp2 have connections to cancer onset, progression, and metastasis." (PMID 35906355, 2022). "Genes containing AS events associated with overall survival are known components of cancer-related pathways, including regulation of transcription (E2F4, ZNF730, GPBP1, POLR2J, SP2, and CIART), cell cycle (E2F4 and GTSE1), or cell-cell adhesion (CEACAM1, MMP14, EPS8L2, AP3D1, AFDN, and PAK4)." (PMID 35044822, 2022). "Sp2 may play a part in promoting cancer by regulating TRIB3 protein, which may be a factor of prognostic and a potential new therapeutic target for HCC." (PMID 32160655, 2020). "We speculate that Sp2 may play a role in promoting cancer by regulating the expression of TRIB3 protein." (PMID 32160655, 2020). "In this study, the role of Sp2 in promoting cancer may be related to the feedback effect of TRIB3 in ERS." (PMID 32160655, 2020). "Sp2 may play a role in promoting cancer by regulating TRIB3 protein, which may be a prognostic factor and a potential new therapeutic target for HCC." (PMID 32160655, 2020). "In GC, miR-638 has been reported down-regulated in cancer tissues and could suppress GC cell proliferation by targeting Sp2 and cyclinD1." (PMID 29296232, 2017). "Since the functional differences between sp1 and sp2 isoforms are still unknown, they may be crucial for a unique function of EMX2 in cancer cells." (PMID 40564092, 2025). "However, an experimental approach is needed to verify the cooperation between H2A.Z and TFs such as SP2, ZNF384, YY1, NRF1, and NFYA in the transcriptional misregulation in cancer." (PMID 35317119, 2021).
tumor (16 papers, 2009 to 2025). "The results of WB and IHC study confirmed that SP2 expression was conspicuously up‐regulated in tumor tissues of HCC, which was strongly linked with the progression and poor prognosis of HCC patients." (PMID 32160655, 2020). "Our clinical results showed Sp2 overexpression was positively correlated not only with tumor stage but also with lymph node metastasis." (PMID 32160655, 2020). "Compared with ANT, Sp2 expression in HCC tissues was significantly up‐regulated, which was strongly associated with stage of tumor and poor prognosis of patients." (PMID 32160655, 2020). "Analysis of paired HCC/ ANT liver tissue data set in The Cancer Genome Atlas (TCGA) showed that Sp2 expression in tumor tissues was obviously higher than normal liver tissues in patients with HCC." (PMID 32160655, 2020). "Accordingly, it can be considered that SP2 should have a certain impact on tumor migration and invasion." (PMID 32160655, 2020). "Assuming that as a cell dies its cell membrane becomes permeable to 7-AAD, tumor cells Sp2/0-Ag14, U937 or REH were infected with rotavirus isolates WT1-5, TRUY, WWM, WTEW or ECwt at a MOI of 0.8." (PMID 26828934, 2016). "Moreover, SP2 was lowly expressed in tumor tissues and associated with a good prognosis, while MYBL2 was highly expressed in tumor tissues and associated with a poorer prognosis." (PMID 37638005, 2023). "As exemplarily shown for sp2-specific TCRs, again only peptide-loaded tumor cells were recognized." (PMID 33875134, 2021). "After detailed clinicopathological analysis, it was found that the expression of Sp2 was positively correlated with tumor size (P = .041), lymph node metastasis (P = .032), clinical stage (P = .011), but did not relate to the histological grade, gender and age of patients." (PMID 32160655, 2020). "Sp1 and Sp2 made up 39.59 and 22.44% of the tumor cells respectively." (PMID 28148223, 2017). "sp2-Iminosugar-type castanospermine analogues have been shown to exhibit anti-tumor activity." (PMID 24124558, 2013). "These HNSC tumor tissues were collected from patients across North Carolina as part of our CHANCE study and assigned to categories (e.g., DP, SP1, SP2, or DN) according to the clinical assay results." (PMID 36148399, 2022). "EGR1 is a direct regulator of many tumor suppressor genes, also SP TF family members (SP1 and SP2) are involved in gene regulation in tumors." (PMID 34282050, 2021). "Our results have found that the high expression of SP2 is positively related to a series of factors in HCC, which include poor prognosis, clinical stage, lymph node metastasis, and tumor size." (PMID 32160655, 2020). "We found that Sp2 expression was significantly up‐regulated in HCC tissues, which was closely related to tumor staging and poor prognosis of patients." (PMID 32160655, 2020). "PKM2 is up-regulated in tumor cells, and is under control of Ras and transcription factors HIF-1, SP1, and SP2." (PMID 19221597, 2009). "We also found that the binding proficiency of the Sp transcription factor family (including SP1, SP2, SP4, and SP5) (Rows 17–20) could bind GC/GT-rich promoter elements by its zinc finger structure and play a critical role in tumor growth and metastasis." (PMID 37833332, 2023). "It is further found that the down‐regulation of Sp2 not only decreases the proliferation rate of HCC cells but also significantly inhibits the invasion and migration ability of cells, as well as promoted the apoptosis of tumor cells." (PMID 32160655, 2020).
infection (9 papers, 2010 to 2025). The state of being infected such as from the introduction of a foreign agent such as serum, vaccine, antigenic substance or organism. "Infection of Sp2cko/cko MEFs with a retrovirus expressing Cre recombinase resulted in a time-dependent deletion of the floxed Sp2 alleles and complete loss of the Sp2 protein at seven days post-infection." (PMID 20221402, 2010). "Retroviral Cre-infection of Sp2cko/cko-vSp2 led to a complete depletion of the floxed Sp2 alleles as well." (PMID 20221402, 2010). "Results obtained in this work highlight the properties of the sp2-isolated strain to inhibit in vitro development of A. hydrophila and reduce pathogen infection capacity in Tilapia." (PMID 39045133, 2024). "The presence also of close orthologs of SmSP2 in Fasciola gigantica and C. sinensis suggests a general role for SP2 during infection in the mammalian host." (PMID 24676141, 2014). "First we infected Sp2cko/cko MEFs with a retroviral expression vector for Sp2 (pBABE-vSp2-puro), using infection with the corresponding empty vector (pBABE-puro) as a control." (PMID 20221402, 2010). "Infectious titers were significantly higher for all the combined isolates as compared with those of ECwt, particularly at 10 and/or 12 h.p.i. in Sp2/0-Ag14 cells, whereas only WTEW and WWM exhibited higher infectious titers in Sp2/0-Ag14 cells at the last post-infection times." (PMID 26828934, 2016). "SP2 was significantly downregulated in HKDM infected with the WT strain compared to HKDM infected with the ΔeseG strain at both 5 and 7 h post-infection (PI)." (PMID 40637600, 2025). "Reduced SP2 and ATF3 may decrease inflammation further, dampening macrophage responses and limiting adaptation to stress within the infection environment." (PMID 40637600, 2025). "While this bottleneck at early stages of S.Tm θ infection was predominantly sp22-mediated, at the highest CFU/g achieved by this strain (81,500 CFU/g), there was evidence of infection of macrophage (sp8 cells) as well as neutrophils (sp1, sp2, sp6)." (PMID 40462990, 2025).
cardiac diseases (1 paper, 2022). "Taken together, our results suggest that FB_sp2 may serve a crucial role in other cardiac diseases besides MI, and other subpopulations like FB_sp1 and FB_sp3 may also be associated with some specific cardiac diseases." (PMID 35252172, 2022).
SP2 also shares sentences with these, for which no sentence is quoted: acute kidney injury (1 paper); asthma (1); autism (1); bacteremia (1); cardiovascular diseases (1); colitis (1); colon cancers (1); colorectal cancer (1); leishmaniasis (1); leukemia (1); Lung Squamous Cell Carcinoma (1); malaria (1); nasopharyngeal carcinoma (1); neurodevelopmental disorder (1); oral squamous cell carcinoma (1); Rotavirus infection (1); Tay-Sachs disease (1).